TFPI2 (tissue factor pathway inhibitor 2)
Diseases named in the same sentence as TFPI2 in open-access papers (continued):
Sharing a sentence is not in itself a finding about the gene and the disease.
breast cancer (continued). "As microRNA-494 (miR-494) protects against breast cancer progression, we investigated whether miR-494 is involved in the regulation of TFPI-2 in MCF-7 breast cancer cells." (PMID 32132611, 2020). "In conclusion, TFPI2 might function as potential prognostic biomarker for breast cancer, and a potential novel target for the breast cancer therapy." (PMID 32248791, 2020). "The expression of TFPI2 was first investigated in breast cancer tissues and cell lines." (PMID 32248791, 2020). "In vivo subcutaneous xenotransplanted tumor model also revealed that ectopic expression of TFPI2 could suppress in vivo tumorigenic ability of breast cancer." (PMID 32248791, 2020). "Moreover, in vitro functional assays revealed that over-expression of TFPI2 inhibited cell viability, proliferation, migration and invasion of breast cancer cells, confirming the clinical results of TFPI2 in breast cancer." (PMID 32248791, 2020). "To investigate whether the association between miR-494 and TFPI-2 could be relevant in a clinical setting, we examined the relationship between TFPI-2 mRNA and miR-494 levels in tumors from breast cancer patients." (PMID 32132611, 2020). "In addition, immunohistochemistry also showed that TFPI2 expression was negatively correlated to metastatic property of breast cancer." (PMID 32248791, 2020). "The effect of TFPI2 on EMT in breast cancer needs to be further investigated." (PMID 32248791, 2020). "In consistent with previous studies, TFPI2 was down-regulated in breast cancer tissues." (PMID 32248791, 2020). "Consequently, TFPI-2 has been proposed as a tumor suppressor and a potential prognostic marker in breast cancer, however, little is known about the regulation of TFPI-2 expression after transcription." (PMID 32132611, 2020). "Tissue factor pathway inhibitor 2 (TFPI2), a member of the Kunitz-type serine proteinase inhibitor family, has been deemed as a tumor suppressor in several neoplasms, such as bladder cancer, cholangiocarcinoma, small cell lung cancer, and breast cancer." (PMID 31186379, 2019). "Our results revealed a biological activity of TFPI-2 in the nucleus, which suggests that one of the mechanisms that TFPI-2 suppresses migration and invasion of breast cancer cells could be mediated by the regulation of MMP-2 expression." (PMID 29051606, 2017). "Our results suggest that one of the mechanisms by which TFPI-2 inhibits breast cancer cell invasion could be via the regulation of MMP-2 gene transcription." (PMID 29051606, 2017). "The purpose of current study is to reveal the potential correlation between TFPI-2 expression level and clinicopathologic features by examining the expression level of TFPI-2 in tumor samples, in order to provide some meaningful insights to its value as a prognostic factor in breast cancer." (PMID 23497249, 2013). "The reduction of TFPI-2 expression may weaken the inhibition of MMPs and plasmin, promote the development of malignant behavior in breast cancer." (PMID 23497249, 2013). "TFPI-2 expression in breast tumors is a potential prognostic tool for breast cancer patients." (PMID 23497249, 2013). "Low or negative expression of TFPI-2 is associated with breast cancer progression, recurrence and poor survival outcome after breast cancer surgery." (PMID 23497249, 2013). "The result suggests that breast cancer patients with lower level of TFPI-2 tend to present more advanced cancer features such as larger tumor, skin involvement, positive lymph nodes, poorer histologic grade, later clinical stage, presence of vessel invasion and so forth." (PMID 23497249, 2013). "Exogenous expression of TFPI-2 may inhibit the malignant behavior of breast cancer cell line MDA-MB-435 in nude mice." (PMID 23497249, 2013).
breast cancer (continued). "It is demonstrated that the downregulation of TFPI-2 expression was significantly correlated with the promoter hypermethylation in some cancer lesions and cell lines, such as nasopharyngeal carcinoma, hepatocellular carcinoma, lung cancer and breast cancer." (PMID 22208663, 2012). "In this regard, Guo and co-workers demonstrated a decreased binding of KLF6 to its DNA binding sequence on the Tissue Factor Pathway Inhibitor-2 (TFPI-2) gene due to CpG hypermethylation in highly invasive breast cancer cell lines, suggesting a tumor suppressor function of KLF6." (PMID 20126619, 2010). "In this study, we found that the CpG islands in TFPI-2 promoter was hypermethylated in highly invasive breast cancer cell line, and DNA methylation in the entire promoter region caused TFPI-2 repression by inducing inactive chromatin structure and decreasing KLF6 binding to its DNA binding sequence." (PMID 18053161, 2007). "In addition, the mutation SM5 and SM6 decreased the promoter activity most significantly (P < 0.01) and this region contains the core matrix of KLF6, indicating that KLF6 plays an important role in the regulation of TFPI-2 in breast cancer cells." (PMID 18053161, 2007). "We hypothesized that both genetic variations and DNA hypermethylation might contribute to the down regulation of TFPI-2 during the progression of breast cancer." (PMID 18053161, 2007). "In vitro studies show that TFPI2 expression inversely correlates with malignancy in cell lines like glioblastoma, lung cancer, prostate cancer, fibrosarcoma, pancreatic ductal adenocarcinoma, gastric cancer, breast cancer, amelanotic melanoma, and thyroid cancer cells." (PMID 40361374, 2025). "Consequently, TFPI-2 has been proposed as a positive prognostic marker in breast cancer." (PMID 39153052, 2024). "Therefore, we hypothesized that the potential regulatory mechanism of TFPI2 on breast cancer dependents on TWIST1." (PMID 32248791, 2020). "While investigating the biological function of TFPI-2 in breast cancer cells, we observed that breast cancer cells, either constitutively expressing TFPI-2 or stimulated with rTFPI-2, have decreased invasive ability that could be reversed by TFPI-2 down-regulation." (PMID 29051606, 2017). "In addition, the constructs -144 to -667 exhibited virtually the same luciferase activity as the -1436 construct, suggesting that nucleotides between -144 to +1 contain the sufficient promoter sequence for the expression of human TFPI-2 gene in breast cancer cell." (PMID 18053161, 2007). "In contrast, tissue factor pathway inhibitor 2 (TFPI-2), a tumor suppressor, binds to MYH9 and actinin-4 to inhibit the proliferation of breast cancer cells." (PMID 39273383, 2024). "However, the mechanism linking TFPI-2 to breast cancer progression remains unknown." (PMID 32248791, 2020). "All these results revealed that the inhibition effect of TFPI2 on breast cancer progression was reversed by TWIST1 over-expression, which confirmed the effect of TFPI2/TWIST1 axis on regulation of breast cancer progression." (PMID 32248791, 2020). "Therefore, TFPI2 may contribute to breast cancer progression." (PMID 32248791, 2020). "TFPI2 inhibited TWIST1 expression to down-regulate integrin α5, and TFPI2/TWIST1/integrin α5 axis contributed to suppression of breast cancer progression, suggesting a novel insight into the treatment of the disease." (PMID 32248791, 2020). "In the present study we examined the effect of miR-494 on TFPI-2 expression and found increased TFPI-2 levels when miR-494 was overexpressed in the breast cancer cell line MCF-7." (PMID 32132611, 2020). "Wound healing and transwell assays showed that over-expression of TFPI2 suppressed cell migration and invasion of MDA-MB-453 cells, suggesting the anti-invasive ability of TFPI2 on breast cancer." (PMID 32248791, 2020). "CpG methylation in the promoter of TFPI2 inhibits binding ability between Kruppel-like factor 6 (KLF6) and TFPI2 in breast cancer." (PMID 32248791, 2020).
breast cancer (continued). "TFPI-2 mRNA and protein levels increased after transfection with miR-494 mimic, and TFPI-2 mRNA and miR-494 levels correlated positively in tumors from breast cancer patients." (PMID 32132611, 2020). "These experiments suggest that TFPI-2 decreases MMP-2 mRNA expression and subsequently the protein’s activity in breast cancer cells." (PMID 29051606, 2017). "TFPI-2 is downregulated in many aggressive tumors, such as gliomas, non-small cell lung cancer (NSCLC), breast cancer (BC), melanoma, colorectal cancer (CRC), pancreatic cancer (PC), hepatocellular carcinoma (HCC), gastric stromal tumor, cervical cancer, and prostate cancer." (PMID 39153052, 2024). "The results demonstrated thatmetastatic breast cancer tissues had the lowest expression of TFPI2, while non-metastatic breast cancer tissues showed higher and normal breast tissues presented the highest expression of TFPI2." (PMID 32248791, 2020). "Reciprocally, we isolated MRX7A, SDF2, TFPI2 and TIMP1 specifically from H1299RASSF1A ECM which, conversely to above, are positively correlated with overall survival in lung adenocarcinoma or breast cancer patients (Fig EV2A)." (PMID 31268606, 2019). "Among the identified transcripts, downregulation of COL6A2, SERPINA1, CCBE1, TFPI2, THBS1 and COL8A1 have been shown to promote migration and invasion of malign breast cancer cells, aggravate metastatic spread and result in poor prognosis of breast cancer patients." (PMID 31848385, 2019). "We found that, compared with patients with TFPI-2 positive breast cancer, patients with TFPI-2 negative had higher proportion of lymph node metastasis and poor differentiation in histology and more common vessel invasion." (PMID 23497249, 2013). "Treatment of MDA-MB-435 with 5-aza-2'-deoxycitidine, the most commonly used demethylation agent, obviously restored TFPI-2 expression in a concentration-dependent manner, indicating that the down regulation of TFPI-2 in breast cancer cells is related with DNA hypermethylation." (PMID 18053161, 2007). "However, the effect and mechanism involved in the regulation of TFPI2 on breast cancer have not been reported." (PMID 32248791, 2020). "Taken together, these observations suggest that antisense-driven silencing of TFPI-2 is not restricted to breast cancer and may also occur in colon cancer." (PMID 23703216, 2013). "TFPI-2 could not be detected in highly invasive breast cancer cell line (MDA-MB-435), while it was expressed in low invasive breast cancer cell lines (MCF-7 and T47D)." (PMID 18053161, 2007). "We found that both protein and mRNA of TFPI-2 could not be detected in highly invasive breast cancer cell line MDA-MB-435." (PMID 18053161, 2007). "Our study showed that human breast cancer cells exhibited a differential pattern of TFPI-2 expression, with high invasive breast cancer cells (MDA-MB-435) showing no expression of TFPI-2 at all, while much higher levels of TFPI-2 expression were observed in lower invasive MCF-7 and T47D." (PMID 18053161, 2007). "Immunohistochemistry results showed up-regulation of TWIST1 in breast cancer tissues, and a significantly negative correlation between TFPI2 and TWIST1 in breast cancer was determined via bivariate correlation analysis." (PMID 32248791, 2020). "We further stratified these 156 breast cancer patients as TFPI-2 positive and TFPI-2 negative groups according to the TFPI-2 staining of tumor sections." (PMID 23497249, 2013).
glioma (20 papers, 2005 to 2025). A benign or malignant brain and spinal cord tumor that arises from glial cells (astrocytes, oligodendrocytes, ependymal cells). "The association was confirmed in the levels of AC003092.1 and TFPI2 in high-grade gliomas as well as GBM cell lines." (PMID 36287118, 2022). "This is supported by the observation that decreased levels of TFPI-2 associate with increased tumour invasion and metastasis in a number of cancers, particularly more aggressive cancers such as glioma and pancreatic cancer." (PMID 23703216, 2013). "Silencing of the TFPI-2 gene associated with hypermethylation of the promoter has recently been described in several cancer cell lines derived from choriocarcinoma, glioma, fibrosarcoma, breast and prostate cancers." (PMID 15685245, 2005). "AC003092.1 boosts TFPI2 through miR-195 inhibition, reducing glioma and gallbladder cancer proliferation." (PMID 40361374, 2025). "TFPI2 downregulation, largely due to promoter hypermethylation, is common in many cancers, including glioma, lung, breast, melanoma, colorectal, pancreatic, liver, gastric, oral, thyroid, cervical, prostate, and bladder cancers." (PMID 40361374, 2025). "As far as the central nervous system is concerned, high levels of TFPI-2 have been confirmed in normal brain tissue, whereas gliomas and anaplastic astrocytomas express greatly reduced amounts." (PMID 39153052, 2024). "A different pattern was identified in the case of the TFPI-2 antigen, which had the strongest expression in low-grade gliomas." (PMID 33947134, 2021). "The results of qRT-PCR validated the AC003092.1 and TFPI2 levels in high-grade glioma and glioblastoma cell lines." (PMID 33815468, 2021). "With regard to TFPI-2, our own results are consistent with the reports of other authors who observed the loss of TFPI-2 expression in glioma tissues with increasing tumor malignancy." (PMID 33947134, 2021). "We validated the positive correlation between the expression of AC003092.1 and TFPI2 in high-grade gliomas and glioblastoma cell lines." (PMID 33815468, 2021). "The correlation between AC003092.1 and TFPI2 in 11 patients with high-grade gliomas, 5 patients with low-grade gliomas, and 7 glioblastoma cell lines was investigated using RT-qPCR." (PMID 33815468, 2021). "In terms of these considerations, the role of the tissue factor-dependent blood coagulation pathway TFPI and TFPI-2 inhibitors in the control of glial tumor growth and in the coagulation process in loco is interesting." (PMID 33947134, 2021). "We quantified AC003092.1 and TFPI2 levels in 11 high-grade gliomas, 5 low-grade gliomas, and 7 GBM cell lines." (PMID 33815468, 2021). "While TFPI2 is downregulated or lost during tumor progression in human glioma, induction of TFPI2 in glioma cells resulted in less invasive phenotype." (PMID 32406600, 2020). "TFPI-2 is able to inhibit the growth, invasion and metastasis of glioma, lung cancer, prostate cancer, laryngeal cancer and pancreatic cancer." (PMID 24396436, 2014). "The tumor-suppressive functions of TFPI-2 have been demonstrated in several human malignancies such as lung cancer, prostate cancer, glioma, melanoma and esophageal carcinoma." (PMID 21062455, 2010). "Transcriptional silencing of the TFPI-2 gene by promoter hypermethylation was recently demonstrated in human glioma cells and choriocarcinoma cells." (PMID 15685245, 2005). "Histone deacetylation is another potential mechanism for TFPI-2 gene silencing in cancer cells since trichostatin A, which inhibits the histone deacetylase, was shown to be effective in inducing TFPI-2 mRNA synthesis in glioma cells." (PMID 15685245, 2005). "A decrease in TFPI-2 mRNA level measured by Northern blotting and in situ hybridisation has previously been demonstrated in other cancers, particularly in human gliomas." (PMID 15685245, 2005).
glioma (continued). "Interestingly, the expression of TFPI-2 decreases with increasing degree of malignancy in multiple neoplasms (gliomas, breast, colon, pancreatic, laryngeal, endometrial and renal cancers)." (PMID 39153052, 2024). "Interestingly, proapoptotic signaling pathways and apoptosis were observed in human glioma cell lines upon TFPI-2 restoration." (PMID 33947134, 2021). "Finally, we validated the AC003092.1 and TFPI2 transcript levels in high-grade gliomas, low-grade gliomas, and GBM cell lines." (PMID 33815468, 2021). "TFPI2 was also related to the occurrence and development of glioma." (PMID 33815468, 2021). "In addition, TFPI-2 antigens were identified in the vascular walls of gliomas of various levels of malignancy." (PMID 33947134, 2021). "Given the similar co-expression profile in TMZ-resistant glioma cells and the close location relationship of lncRNA AC003092.1 and TFPI-2, we hypothesized whether lncRNA AC003092.1 regulated TMZ chemoresistance in glioma cells by targeting TFPI-2 expression." (PMID 30442884, 2018). "Recent studies have demonstrated that the TFPI-2, a Kunitz-type proteinase inhibitor, could inhibit cell migration, proliferation, and promote cell apoptosis in glioma cells." (PMID 30442884, 2018). "In several types of malignancies, such as choriocarcinoma, glioma, prostate cancer, pancreatic carcinoma and lung cancer, TFPI-2 has significantly demonstrated tumor-suppressive functions during tumor cell invasion, metastasis, apoptosis, proliferation and angiogenesis." (PMID 22208663, 2012). "The results of this study suggested that AC003092.1, an immune-related eRNA, was associated with a glioma-immunosuppressive microenvironment, which indicated important association with survival in GBM specimens and the upregulated expression of target gene, TFPI2." (PMID 36287118, 2022). "Indeed, the human TFPI-2 has been previously related with cell invasion in glioma." (PMID 32545233, 2020). "It has been shown that TFPI-2 is down-regulated via epigenetic silencing mechanisms including promoter hypermethylation and histone deacetylation in several types of tumor, such as pancreatic ductal adenocarcinoma, melanoma, hepatocellular carcinoma, gastric carcinoma, and glioma." (PMID 25179542, 2014). "Similarly, immunoexpression of TFPI-2 has been studied in many other different tumors (laryngeal, breast, gastric, colon, pancreatic, renal, endometrial cancer and glial neoplasms) and the expression of TFPI-2 diminished with an increasing degree of malignancy." (PMID 22208663, 2012). "In support of its functioning as a tumor suppressor, TFPI-2 is epigenetically silenced in aggressive cancers including, among others, colorectal cancer or CRC, glioma, NSCLC, pancreatic cancer or PC, BC, melanoma, HCC, and oral squamous cell carcinoma (OSCC)." (PMID 39153052, 2024). "A strong expression of TFPI-2, PS, TM, PAI-1 was observed in lower-grade gliomas, while an intensive color immunohistochemical (IHC) reaction for the presence of TFPI antigens was detected in higher-grade gliomas." (PMID 33947134, 2021). "They found AC003092.1 located at about 32 kb from TFPI2 and revealed that TFPI2 was the target gene of AC003092.1 in temozolomide-resistant glioma cells." (PMID 33815468, 2021). "TFPI-2 may also induce apoptosis, as described in TFPI-2-positive GBM cell lines (SNB-19) and low-grade gliomas (Hs683)." (PMID 39153052, 2024). "TFPI-2 positive GBM, as well as low-grade glioma cell lines, demonstrated enhanced apoptosis, while in normal glial tissue and in TFPI-2 negative glioma cell lines, apoptosis was absent." (PMID 33947134, 2021). "In high-grade gliomas and glioblastoma cell lines, there was a significantly positive correlation between AC003092.1 and TFPI2 (high-grade gliomas: Spearman rank correlation coefficient r = 0.8614, p < 0.001; glioblastoma cell lines: Spearman rank correlation coefficient r = 0.8200, p < 0.05)." (PMID 33815468, 2021).